SCRN1 (secernin 1)
Description:
Regulates exocytosis in mast cells. Increases both the extent of secretion and the sensitivity of mast cells to stimulation with calcium (By similarity).
Synonyms: KIAA0193; SES1
Tractability: PROTAC: ubiquitination databases record sites on it; its protein half-life has been measured.
Gene: Protein-coding gene on chromosome 7 (29,920,104 to 29,990,289, reverse strand). Ensembl gene ENSG00000136193.
Subcellular location: Cytoplasm
Subcellular location (Human Protein Atlas): Cytosol
Gene Ontology:
Molecular function: protein binding; cysteine-type exopeptidase activity; dipeptidase activity
Biological process: exocytosis; proteolysis; regulation of synaptic vesicle cycle
Cellular component: nuclear membrane; nucleus; cytoplasm; presynapse
Genetic constraint (gnomAD): Loss-of-function variants: 19 observed, 44.71 expected, observed/expected ratio (o/e) 0.42, 90% interval 0.29 to 0.62. The upper end of that interval is the gene's LOEUF score, 0.62, which puts it in group 2 of 6, group 1 being the genes least tolerant of losing a copy. Missense variants: 447 observed, 536.59 expected, observed/expected ratio (o/e) 0.83, 90% interval 0.77 to 0.9. Synonymous variants: 183 observed, 191.79 expected, observed/expected ratio (o/e) 0.95, 90% interval 0.85 to 1.08.
Homologues: Orthologues: chimpanzee SCRN1 (98% identical), dog SCRN1 (91% identical), guinea pig SCRN1 (90% identical), rabbit SCRN1 (90% identical), rat Scrn1 (90% identical), pig SCRN1 (90% identical), mouse Scrn1 (88% identical), macaque SCRN1 (83% identical), tropical clawed frog scrn1 (63% identical), Drosophila melanogaster CG10098 (24% identical). Paralogues in human: SCRN3 (52% identical), SCRN2 (52% identical).
Diseases named in the same sentence as SCRN1 in open-access papers:
SCRN1 is named in the same sentence as 33 diseases in open-access papers, as found by Europe PMC text mining. Sharing a sentence is not in itself a finding about the gene and the disease. The quoted sentences say what the papers report.
colorectal cancer (6 papers, 2011 to 2023). A primary or metastatic malignant neoplasm that affects the colon or rectum. "However, these conclusions may be tissue specific as SCRN-1 expression has also been proposed as a prognostic marker in colorectal cancer where elevated expression was associated with a worse prognosis." (PMID 24090399, 2013). "Recently, SCRN1 was reported to be correlated with the prognosis of colorectal cancer and gastric cancer, but its functional effects on oral squamous cell carcinoma (OSCC) remain unclear." (PMID 37691034, 2023). "Knockdown of SCRN1 significantly reduced tumour cell growth in colorectal cancer." (PMID 34109184, 2021). "Moreover, the upregulation of secernin-1 in colorectal cancer compared to normal colorectal tissue correlates with clinicopathological data and is associated with poor prognosis." (PMID 25667921, 2015). "SCRN1 was reported in Perou’s breast cancer intrinsic genes list and was speculated to be a prognostic marker in colorectal cancer." (PMID 24098497, 2013). "SCRN1, a marker of colorectal cancer, was also over-expressed in ccRCC relative to papillary." (PMID 21818257, 2011).
synovial sarcoma (5 papers, 2012 to 2017). "The poor prognostic significance of SCRN1 expression in colon cancer, is contrary to that reported in synovial sarcoma." (PMID 28191313, 2017). "SCRN1 expression levels were reported to be correlated with poor prognosis in synovial sarcoma and colon cancer." (PMID 25814779, 2015). "Secernin-1 (SCRN-1) regulates exocytosis in mast cells and has recently been proposed as a prognostic marker in synovial sarcoma where high expression is associated with a better prognosis possibly due to a higher grade of differentiation." (PMID 24090399, 2013). "The prognostic value of secernin-1 was further examined in 45 newly enrolled patients with synovial sarcoma." (PMID 22778956, 2012). "SCRN1 was identified as a prognostic biomarker for synovial sarcoma and could accurately predict the overall and metastasis-free survival rates of patients." (PMID 25814779, 2015). "It is not clear how secernin-1 is involved in the malignant features of synovial sarcoma, but the association of secernin-1 with the prognosis seems to be significant, and it would be worthwhile continuing the validation of this study." (PMID 22778956, 2012). "As is the case with other biomarker studies, the functional backgrounds of biomarker molecules remain unclear yet but it would be useful to investigate the functional properties of secernin-1 and GST-P1 in the malignant features of synovial sarcoma, in parallel with validation studies." (PMID 22778956, 2012).
Alzheimer disease (4 papers, 2019 to 2025). A progressive, neurodegenerative disease characterized by loss of function and death of nerve cells in several areas of the brain leading to loss of cognitive function such as memory and language. "Elevated levels of PDCD5, ENO1, CHI3L1, PP3R1 and SCRN1 have been observed in CSF from individuals with Alzheimer disease." (PMID 36721240, 2023). "SCRN1 or secernin-1 is interesting since it binds to phosphorylated tau in neurofibrillary tangles present in Alzheimer but not other non-Alzheimer disease tauopathies." (PMID 36721240, 2023). "Little is known about the physiological function of SCRN1 and its role in Alzheimer’s disease (AD) and other neurodegenerative diseases has not been studied." (PMID 31796108, 2019).
colon cancer (4 papers, 2010 to 2017). "Indeed, secernin 1 expression was upregulated in gastric cancer and colon cancer where it was implicated in cell growth, and it was found to be one of several novel genes overexpressed in Barrett's esophagus high-grade dysplasia." (PMID 20069063, 2010). "In colon cancer, SCRN1 expression promoted exocytosis secretion of MMP2 and MMP, while silencing this gene reduced MMP2 secretion, inhibited cell proliferation and decreased invasion capability." (PMID 28191313, 2017). "In multivariate analysis, SCRN1 expression was confirmed to be an independent prognosis predictor in colon cancer." (PMID 25814779, 2015). "In conclusion, our results demonstrated that SCRN1 mRNA and protein expression were elevated in colon cancer." (PMID 25814779, 2015). "In this study, we demonstrated the aberrant overexpression of SCRN1 at mRNA and protein level in colon cancer." (PMID 25814779, 2015). "In this study, in agreement with a previous study, we demonstrated that SCRN1 expression is upregulated in colon cancer tissues compared to paired normal mucosa using qPCR and western blot." (PMID 25814779, 2015). "Using immunohistochemistry, we confirmed that SCRN1 protein was overexpressed mainly in the cell cytoplasm and that the staining intensity and extent were lower in normal mucosa than in colon cancer tissues and LNM." (PMID 25814779, 2015). "The result was in accordance with our previous work using bioinformatics analysis and further confirmed SCRN1 upregulation in colon cancer." (PMID 25814779, 2015). "In the present study, we investigated SCRN1 gene expression at protein and mRNA level in 40 colon cancer tissues paired with adjacent normal mucosa." (PMID 25814779, 2015). "Secernin-1 is described as being deregulated in different carcinomas: secernin-1 is upregulated in colon cancer, in gastric cancer, and in Barrett's esophagus associated with high-grade dysplasia compared to nondysplastic Barrett's esophagus." (PMID 25667921, 2015). "Kaplan-Meier survival curves with the log-rank test for OS and DFS were undertaken to elucidate the relationship between colon cancer SCRN1 expression and patient survival." (PMID 25814779, 2015). "Western blot revealed that SCRN1 protein expression was elevated in colon cancer tissue compared with adjacent normal mucosa." (PMID 25814779, 2015). "Experiments in colon cancer cell lines were carried out to study SCRN1 biological functions in vitro." (PMID 25814779, 2015). "SCRN1 protein expression in tissue microarrays (TMAs) was also detected to assess the expression pattern in colon cancer tissue." (PMID 25814779, 2015). "SCRN1 protein expression was moderate to strong in 53.0% (62/117) of colon cancer tissues." (PMID 25814779, 2015). "We hypothesized that, in colon cancer cells, SCRN1 regulates the secretion of MMPs to promote cell proliferation and invasion." (PMID 25814779, 2015). "Taken the expression pattern and clinical pathological significance into consideration, we hypothesized that SCRN1 contributes to the colon cancer progression through accelerating cancer cell proliferation and invasion." (PMID 25814779, 2015). "In addition, we identified the significance of SCRN1 in colon cancer progression for the first time." (PMID 25814779, 2015). "SCRN1 expression was knocked down by siRNA in human colon cancer cells RKO and HCT116." (PMID 25814779, 2015). "The SCRN1 gene product has been shown to be overexpressed in gastric and colon cancer." (PMID 25814779, 2015). "However, the expression pattern and cellular localization of SCRN1 protein, its clinical significance, and its mechanism of action in the progression of colon cancer remain poorly understood." (PMID 25814779, 2015). "Additionally, only few studies addressing the significance of SCRN1 and its mechanism of action in the progression of colon cancer have been reported." (PMID 25814779, 2015).
colon cancer (continued). "Furthermore, inhibiting SCRN1 expression may be a novel targeted therapy to prevent tumor metastasis and to improve the outcomes of patients with colon cancer." (PMID 25814779, 2015). "However, whether SCRN1 influences the biological behavior of colon cancer cells through other mechanisms remains unclear." (PMID 25814779, 2015). "Furthermore, we analyzed the relationship between SCRN1 expression and clinicopathological features and investigated whether SCRN1 could be a predictor of prognosis for patients with colon cancer." (PMID 25814779, 2015). "Among the 40 specimens of colon cancer, 34 showed higher SCRN1 expression compared with paired normal mucosa." (PMID 25814779, 2015).
gastric cancer (4 papers, 2010 to 2023). A primary or metastatic malignant neoplasm involving the stomach. "Genotyping analysis of these SNPs in the case and control individuals manifested that the variation genotype C > T in rs6976789 of SCRN1 gene had a significant association with high gastric cancer risk." (PMID 35330456, 2022). "The overall outcomes of this research manifested a pivotal role of SCRN1 and its single nucleotide polymorphisms in susceptibility, prognosis, and development of gastric carcinoma." (PMID 35330456, 2022). "Furthermore, the cumulative survival score of gastric carcinoma carriers with T.T. genotypes of SCRN1 rs6976789 was lower than CC and C.T. genotypes." (PMID 35330456, 2022).
tauopathies (4 papers, 2019 to 2023). "Here, we show that Secernin-1 (SCRN1) is a new protein that interacts with pTau in select tauopathies." (PMID 31796108, 2019). "Logically, the different conformation of tau aggregates in other primary tauopathies could prevent interaction with SCRN1." (PMID 31796108, 2019). "As such, SCRN1 has potential as a novel therapeutic target and could serve as a useful biomarker to distinguish AD from other tauopathies." (PMID 31796108, 2019). "The absence of SCRN1 accumulation in pTau lesions present in the 4R-specific tauopathies CBD and PSP raised the possibility that SCRN1 preferentially colocalizes with 3R-tau isoforms, however the lack of SCRN1 accumulation in the 3R-tau specific PiD showed that this was not the case." (PMID 31796108, 2019). "In conclusion, we have shown that the novel protein SCRN1 is associated with neurofibrillary tangles in AD, DS and PART but not in other tauopathies." (PMID 31796108, 2019). "The importance of analyzing the protein aggregates for each neurodegenerative disease can be highlighted by a recent study by Pires and colleagues who demonstrated that Secernin 1 co‐localizes with p‐Tau in cases of AD but not other Tauopathies including PiD, CBD, or PSP." (PMID 36847488, 2023). "Here, we present a comprehensive neuropathological study showing that SCRN1 is a novel protein that accumulates specifically in AD, DS and PART, which are 3R/4R tauopathies, but not in other tauopathies that are either 3R or 4R tauopathies." (PMID 31796108, 2019).
Cognitive impairment (2 papers, 2019 to 2023). Abnormal cognition is characterized by deficits in thinking, reasoning, or remembering. "In studies of diseases related to cognitive impairment such as AD and primary age-related tauopathy, many SCRN1 aggregates were found in NFTs and plaque-related dystrophic neuritis." (PMID 38025258, 2023).
prostate carcinoma (2 papers, 2015 to 2018). A carcinoma that arises from epithelial cells of the prostate gland. "Secernin-1 has been successfully validated as a potential diagnostic biomarker candidate for prostate cancer in tissue using Western blot analysis." (PMID 25667921, 2015). "Although larger-scale validation studies involving more patients are still needed, vinculin and galectin-3 seem to be promising urinary biomarker candidates for recurrent prostate cancer, while secernin-1 seems to be a useful tissue diagnostic biomarker candidate for prostate cancer." (PMID 25667921, 2015). "Validation of secernin-1 expression using tissue Western blots, immunohistochemical staining, and immunohistochemical staining of an independent TMA set showed a significant downregulation of secernin-1 in prostate cancer tissue compared to tumor-free tissue." (PMID 25667921, 2015). "In summary, secernin-1 is up regulated in many tumors, but we and others have demonstrated that secernin-1 is downregulated in prostate cancer tissue compared to tumor-free prostatic tissue." (PMID 25667921, 2015). "Prostate tissue samples analyzed by 2D-DIGE (two-dimensional difference in gel electrophoresis) and mass spectrometry (MS) revealed downregulation of secernin-1 (P < 0.044) in prostate cancer, while vinculin showed significant upregulation (P < 0.001)." (PMID 25667921, 2015). "The decrease in secernin 1, involved in the regulation of intracellular trafficking within the cell is also consistent with the downregulation of secernin 1 that was previously observed in prostate cancer in comparison with normal prostatic tissue." (PMID 29662647, 2018). "Immunohistochemical secernin-1 staining could detect prostate cancer with a sensitivity of 98.0% and a specificity of 99.2% for a threshold score of ≥1 versus <1." (PMID 25667921, 2015). "As secernin-1 expression is identical in inflamed and normal prostate tissue, secernin-1 might be a good biomarker candidate for prostate cancer." (PMID 25667921, 2015). "Thus, secernin-1 is a novel potential biomarker candidate for recurrent prostate cancer." (PMID 25667921, 2015). "2D-DIGE analysis also revealed lower secernin-1 abundance in recurrent prostate cancer compared to nonrecurrent prostate cancer." (PMID 25667921, 2015). "Thus, it appears that secernin-1 is mostly expressed in the basal layer and could possibly be lost during the transition from benign prostate tissue to PIN and prostate cancer." (PMID 25667921, 2015). "Secernin-1 level in urine has not been detected by MRM-MS thus far, so the potential of secernin-1 as a noninvasively obtained biomarker candidate in urine from prostate cancer patients is still part of our ongoing work." (PMID 25667921, 2015).
Anxiety (1 paper, 2023). Intense feelings of nervousness, tension, or panic often arise in response to interpersonal stresses. "When considering NPDs of interest, depression, and anxiety alone, the strongest pleiotropic effects of single genes, i.e. highest number of associations with disorders, were observed for PFN2, HTRA1, SCRN1, ATAT1, and SYN3." (PMID 37461513, 2023).
bipolar disorder (1 paper, 2025). A disorder of the brain that causes unusual shifts in mood, energy, activity levels and the ability to carry out day-to-day tasks. "SCRN1, identified to have effects on bipolar disorder, is a novel phosphorylated tau binding protein that has been shown to be abundant in amyloid plaques and has been recently identified as shared in cross-trait analyses between bipolar disorder and inflammatory bowel disease." (PMID 40281223, 2025).
dementia (1 paper, 2019). Loss of intellectual abilities interfering with an individual's social and occupational functions. "We also analyzed SCRN1 distribution in the brain in HCHWA-D, which is a rare autosomal dominant disorder caused by an APP 693 mutation that clinically leads to recurrent hemorrhagic strokes and dementia." (PMID 31796108, 2019). "This is supported by the finding that SCRN1 accumulation is present in AD, DS where co-occurrence of Aβ and Tau is observed, while it is not present in tau-only dementias (PSP, CBD, PiD) or in HCHWA-D that only has accumulation of Aβ." (PMID 31796108, 2019).
lung carcinoma (1 paper, 2016). "Utilizing further RNAi-based synthetic lethal screening, we found that suppression of SCRN1 in erlotinib-resistant clones restores drug sensitivity, suggesting that upregulation of SCRN1 may be a new mechanism for rendering the EGFR mutant-lung cancer cell lines to erlotinib resistance." (PMID 26883194, 2016).
ovarian carcinoma (1 paper, 2021). A malignant neoplasm originating from the surface ovarian epithelium. "Eight immune factors (IFT57, MAL, ANXA4, SCRN1, LTBR, KIFAP3, HSPA5, and LTN1) were positively correlated with poor prognosis of ovarian cancer, whereas six immune factors (PSMB9, FOXJ1, CTSH, MIF, CTSD, and PSMB8) were negatively correlated with poor prognosis of ovarian cancer." (PMID 34109184, 2021).
schizophrenia (1 paper, 2010). A major psychotic disorder characterized by abnormalities in the perception or expression of reality. "Several proteomic studies have identified secernin 1 as being upregulated in the dorsolateral prefrontal cortex of patients with schizophrenia, and consistent with a decline in neuronal function, it was downregulated in the cerebral cortex of sleep-deprived mice." (PMID 20069063, 2010).
uterine disease (1 paper, 2024). "Previously identified fertility-related genes, such as POR and SCRN1, were also revealed in this study as candidate genes corresponding to uterine disease in the transition period." (PMID 38674374, 2024).